BRCA1 (BRCA1 DNA repair associated)
Diseases named in the same sentence as BRCA1 in open-access papers (continued):
Sharing a sentence is not in itself a finding about the gene and the disease.
ovarian carcinoma (continued). "Because BRCA1/2 carriers already possess an underlying risk for ovarian cancer, use of clomiphene citrate in these patients must be carefully monitored and considered on a patient-by-patient basis." (PMID 35685436, 2022). "The ARIEL-4 trial enrolled 349 patients with high-grade epithelial ovarian cancer and a germline (84%) or somatic (16%) BRCA1/2 mutation, who received two or more prior chemotherapy regimens." (PMID 35267543, 2022). "The risk of ovarian cancer in BRCA1 and BRCA2 mutation patients is 44% and 17%, respectively, whereas the lifetime risk of breast cancer is up to 72% in these patients." (PMID 35180738, 2022). "We used whole-exome sequencing (WES) to assess the landscape of somatic mutations in 67 paired primary/recurrent tumors and matched germline samples from 27 BRCA1/2 mutation carriers with breast or ovarian cancer." (PMID 36344544, 2022). "Approximately 11% of unselected ovarian cancer patients in the region of Podkarpacie carry a BRCA1 or BRCA2 causative variants." (PMID 35382848, 2022). "The positive NES value indicates that genes in these gene sets are expressed lower in BRCA1-deficient patients than in BRCA1-proficient patients, which suggests that responses to DNA damage are attenuated in ovarian cancer cells with defective BRCA1." (PMID 35517499, 2022). "In our cohort four of our patients out of 65 (6%) harbored a BRCA1/2 pathogenic germline alteration, we concluded that these cases suffer from hereditary breast and ovarian cancer." (PMID 35986351, 2022). "BRCA1 (Breast Cancer Type 1 Susceptibility Protein) gene mutations in the germline are a hallmark of hereditary breast and ovarian cancers." (PMID 36230683, 2022). "BRCA1 is a well-known tumor suppressor gene, which is frequently mutated in breast and ovarian cancers." (PMID 33884520, 2022). "When inspecting the results above, we particularly noticed that genes involved in the ADRB1-mediated cAMP signaling pathway were dramatically up-regulated in BRCA1-deficient ovarian cancer patients." (PMID 35517499, 2022). "The most important risk factor for ovarian cancer is a family history of breast and ovarian cancer, often in association with inherited variants in BRCA1 and BRCA2 as well as in other breast and/or ovarian cancer susceptibility genes." (PMID 35326583, 2022). "Germline mutation in BRCA1 is associated with breast–ovarian cancer familial susceptibility, also known as hereditary breast and ovarian cancer (HBOC)." (PMID 36551764, 2022). "Molecular analysis on normal tissue identified one PDAC patient as a carrier of a germline BRCA1 pathogenetic variant and, noteworthy, this patient was a member of a family affected by inherited breast and ovarian cancer conditions." (PMID 35625944, 2022). "HR repair is the main pathway for repairing double-strand breaks 25, and BRCA1 and 2 are important proteins involved in this pathway, of which mutations in these genes predispose to occurrence of tumors including ovarian cancer." (PMID 35165509, 2022). "For instance, female BRCA1 PV carriers are at a higher risk for breast and ovarian cancer than BRCA2 PV carriers." (PMID 36497436, 2022). "By targeting multiple oncogenic components, synthetic lethal has shown promising potential as best exemplified by using PARPi to treat BRCA1/2 mutated breast and ovarian cancer." (PMID 36497135, 2022). "Such low BRCA1 expression and high expression of miRNA-9 was associated with platinum sensitivity and longer progression-free survival in ovarian cancer cells." (PMID 35328651, 2022). "Currently, BRCA1/2 genetic testing is suggested for ovarian cancer patients not only for estimating familial risk but also for determining their eligibility for PARP inhibitor therapy." (PMID 35813356, 2022).
ovarian carcinoma (continued). "In unselected ovarian cancer patients, BRCA1 pathogenic variants were more common compared to BRCA2 (20.07% vs. 6.19%)." (PMID 36439508, 2022). "The identification of BRCA1 nonsense variants in patients confers a high risk of breast and ovarian cancer onset as these variants lead to protein truncation and loss of function." (PMID 35837282, 2022). "Inherited susceptibility to ovarian cancer is found in approximately 15% of patients, the vast majority of which have germline heterozygous mutations in the BRCA1 or BRCA2 genes." (PMID 35203410, 2022). "Olaparib increased progression-free survival in BRCA1/2 mutated patients in primary ovarian cancer, and niraparib prolonged progression-free survival regardless of HRD status or BRCA mutations in primary ovarian cancer." (PMID 34980026, 2022). "A microfluidic platform was designed for screening the blood plasma of patients for DNA bearing BRCA1/2 mutations to detect ovarian-cancer-related mutations, as ovarian cancer has a similar mutational origin as breast cancer." (PMID 35208277, 2022). "The mutation of BRCA1 in ovarian cancer has been widely reported, and it is considered to be an important marker of hereditary ovarian cancer." (PMID 36081665, 2022). "Approximately 20–30% of EOC occurs in females with an inherited predisposition; most of these hereditary ovarian cancers are due to germline mutations in BRCA1 and BRCA2 genes." (PMID 35805770, 2022). "Epithelial ovarian cancer patients harboring BRCA1/2 tumor mutations, who underwent germline testing and received PARPi therapy at the Medical University of Vienna (n = 41) were included in the study." (PMID 36143252, 2022). "Ovarian cancers with germline or somatic mutation of BRCA1 or BRCA2, mutation of RAD51C or RAD51D, methylation of BRCA1, or high LOH have all been reported to respond to PARP inhibition." (PMID 35223797, 2022). "The CUC Proforma was piloted with Application 1411—testing for BRCA1/2 germline pathogenic variants in people with breast or ovarian cancer—and subsequently revised following re-assessment of this application (i.e. Application 1411.1)." (PMID 34570356, 2022). "This is less than in other regions of Poland where the frequency of BRCA1 causative founder variants was observed in about 10-13.5% of ovarian cancer patients." (PMID 35382848, 2022). "Almost all breast or ovarian cancers arising in BRCA1/2 germline mutation carriers develop via the inactivation of the remaining allele of the involved gene." (PMID 36361916, 2022). "DCA can modulate the expression of breast cancer type 1 susceptibility protein (BRCA1) and the estrogen receptor and, through these, can control drug sensitivity of ovarian cancer cells." (PMID 35429253, 2022). "High-grade serous ovarian cancer (HGSOC) is the most predominant ovarian cancer, in which BRCA1/2 gene mutation ranges from 3 to 27%." (PMID 36142803, 2022). "As a result, the 3450delCAAG BRCA1 mutation deregulates regulators of cell cycle progression, cell motility, and cell invasion, which can contribute to the metastasis of breast and ovarian cancers." (PMID 35740092, 2022). "Among them, BRCA1/2 mutations are the most frequent and lead to hereditary breast and epithelial ovarian cancer (EOC)." (PMID 36010882, 2022). "Increased mortality due to ovarian cancer can be explained by shared inherited susceptibility genes such as BRCA1 or BRCA2, especially in young women." (PMID 36612726, 2022). "In part 2B, rucaparib was tested in patients with relapsed high-grade ovarian cancer (HGOC) with a germline or somatic BRCA1/2 mutation (g/sBRCAm) who had received at least three cycles of prior chemotherapy." (PMID 35897700, 2022). "Except for breast and ovarian cancer, patients with BRCA1/2 associated HBOC also showed higher risk of prostate cancer, uterine cancer, pancreatic cancer melanoma." (PMID 36463302, 2022).
ovarian carcinoma (continued). "Common genetic variation (represented by single nucleotide polymorphisms (SNPs)) at loci encoding for functional interactors of BRCA1 and/or BRCA2 modify breast and/or ovarian cancer risk in carriers of germline BRCA1 and/or BRCA2 mutations." (PMID 35053516, 2022). "The BRCA1/2 mutations are predominantly observed in breast and ovarian cancer in women and PCa in men." (PMID 35734583, 2022). "Defects in DNA double‐strand break repair, in particular mutations in genes involved in HR, are associated with an increased risk of cancer, with BRCA1/2 mutations in breast and ovarian cancers being one of the most common examples of this." (PMID 35834102, 2022). "Tumor-intrinsic STING signaling facilitates BRCA-1 mutated ovarian cancer cells’ resistance to both PD-L1 and CTLA-4 therapies by upregulating VEGF-A." (PMID 36189283, 2022). "For example, deleterious variation in BRCA1 of homologous recombination pathway causes high risk of breast and ovarian cancer." (PMID 35595529, 2022). "We examined the degree of cancer worry and the course of this worry among BRCA1/2-PV carriers undergoing surgery to prevent ovarian cancer, and identified factors associated with high cancer worry." (PMID 34997316, 2022). "For ovarian cancer, the benefit of BRCA1/2 mutation in overall survival (OS) and in progression free survival (PFS) was not related to stage, histology subtype or grade." (PMID 35267543, 2022). "Among patients with ovarian cancer G1, the all-cause survival was significantly associated with a BRCA1 mutation (HR=4.73, 95%CI 1.45–15.43, p=0.01)." (PMID 35313928, 2022). "The patient inclusion criteria include positive family history of breast or ovarian cancer or HRD mutations in the BRCA1, BRCA2, PALBB2, or FANC genes." (PMID 35328658, 2022). "Such approaches have been shown to be efficacious in treatment of breast and ovarian cancers of BRCA1/2 carriers, as well pancreatic cancers with an inactivation of BRCA1, BRCA2, or PALB2 and an HR deficiency tumor mutation signature." (PMID 36497436, 2022). "There is an increased risk of cancers of the ovary, fallopian tube, and peritoneum in BRCA1/2 mutation carriers." (PMID 35267543, 2022). "For examples, ovary cancer patients with BRCA1 or BRCA2 mutations benefit particularly from Poly ADP-ribose polymerase inhibitor Olaparib while solid tumors with MMR mutations have demonstrated high response rate to immune checkpoint blockade." (PMID 35273153, 2022). "Pathogenic variants of the BRCA1 and BRCA2 genes (BRCA1/2) are established as most significant genetic risk factors for developing breast and ovarian cancers." (PMID 33468216, 2021). "Here, iPSCs were generated from three patients diagnosed with epithelial ovarian cancer, and all carried germline pathogenic mutations in the BRCA1 gene and three unaffected, non-BRCA1 mutation controls." (PMID 34965417, 2021). "Compelling evidence has shown that several interventions are effective in reducing the risk of future breast and ovarian cancer of women with BRCA1 or BRCA2 pathogenic variants." (PMID 34072979, 2021). "Breast cancer susceptibility gene 1 (BRCA1) is a tumor suppressor gene, germline mutations of which are linked to familial breast and ovarian cancers." (PMID 33996823, 2021). "Germline mutations in the coding region of the BRCA1 gene are responsible for familial breast and ovarian cancers." (PMID 34926299, 2021). "Germline variants in other ovarian cancer risk genes are identified in 4–7% of ovarian cancer, and BRCA1/2‐only tumor testing will result in a failure to identify and manage these individuals at increased cancer risk." (PMID 33030818, 2021). "Ovarian cancer risk is also elevated by the presence of these mutations, with one study finding that ovarian cancer occurs in an estimated 44% of BRCA1-positive women and 17% for those with BRCA24." (PMID 34969949, 2021).
ovarian carcinoma (continued). "There was a statistical association between PVs and a family history of ovarian cancer only for PVs in the BRCA1 gene (p < 0.001)." (PMID 33606809, 2021). "Expansion of genetic test beyond BRCA1/2 nearly double the rate of finding germline P/LP variants, thus multigene panel test should be encouraged in ovarian cancer." (PMID 33649982, 2021). "For ovarian cancer, BRCA1 gene mutation is a common pathogenic factor and marker for ovarian cancer." (PMID 34187307, 2021). "Germline mutations of BRCA1/2 are known to be associated with an increased risk of the development of ovarian cancer and breast cancer and are also found in PCs at a frequency of about 4–7%." (PMID 34209310, 2021). "In a large study, LGRs were reported to constitute around 24% of BRCA1/BRCA2 PVs in high-risk breast/ovarian cancer families, while lower rates are reported in other series and in individuals without strong family histories." (PMID 34503154, 2021). "When comparing the various ovarian cancer cells in vitro, the serous and the BRCA1 mutated ovarian cancer cells significantly overexpressed PAFR." (PMID 34571986, 2021). "BRCA1 mutation will increase the risk of developing ovarian cancer to about 40–60%, compared to the cumulative risk of about 1.3% in the general population." (PMID 34571986, 2021). "In our study, we have screened 24 Pakistani cases for germline mutations causative for breast and ovarian cancer subtypes by doing targeted sequencing of BRCA1/BRCA2 genes, with moderate family history provided." (PMID 33773534, 2021). "‘BRCAness’ represents a genetic (or even a phenotypic) impairment of the hereditary breast/ovarian cancer susceptibility BRCA1/2 genes." (PMID 34948122, 2021). "BRCA1 is one breast and ovarian cancer susceptibility gene that plays an important role in DNA damage repair and cell cycle regulation." (PMID 33670664, 2021). "Much of the research on the role of PARP inhibitors in ovarian cancer have been undertaken on patients with BRCA1/2 mutations and deficiencies in the homologous recombination repair pathway." (PMID 33419231, 2021). "To date, the cellular origin and pathogenesis of OVCs are not well understood, but it was established that pathogenic germline mutations in BRCA1 or BRCA2 genes are the main risk factors in the development of ovarian cancer." (PMID 34207450, 2021). "Though BRCA1/2-deficient cancers are sensitive to platinum-based therapy, secondary BRCA1/2 mutations are also responsible for acquired resistance to cisplatin in ovarian carcinomas." (PMID 34616682, 2021). "Pathogenic germline mutations in BRCA1/2 constitute the majority of hereditary breast and/or ovarian cancers worldwide." (PMID 33773534, 2021). "Higher olaparib sensitivity was associated with lower hMOB2 protein levels among these two BRCA1/2 wild-type ovarian cancer cell lines." (PMID 34363951, 2021). "We found two adequate studies on the association between HRT and ovarian cancer risk in BRCA1/2 mutation carriers to include in our review." (PMID 33885953, 2021). "Data regarding the utility of this procedure for patients with germline mutations other than BRCA1/2 that confer ovarian cancer risk are insufficient and require a personalized approach." (PMID 33419231, 2021). "This phenomenon is well documented in the cases of recurrent chemoresistant ovarian cancer which has been shown to reacquire DNA repair proficiency by reversion of BRCA1/BRCA2 mutations or modification of epigenetic marks." (PMID 34283069, 2021). "In 54 families with breast/ovarian cancer, three truncation mutations in the BRCA1 gene and five in the BRCA2 gene were found." (PMID 34202525, 2021). "It is well-known that germline mutations in homologous recombination genes, for example BRCA1/2, predispose individuals to breast and ovarian cancer, and that these mutations are synthetic lethal with poly(ADP-ribose) polymerase (PARP) inhibition." (PMID 34944870, 2021).
ovarian carcinoma (continued). "Studies have shown that patients with breast and ovarian cancer, including fallopian tube and primary peritoneal cancer have high risk for harboring BRCA1/2 mutations." (PMID 32862296, 2021). "The Consortium of Investigators of Modifiers of BRCA1/2 (CIMBA) revealed that the incidence of ovarian cancer is high in patients with germline BRCA mutation in the OCCR in about 30,000 BRCA mutant carriers in 33 countries around the world." (PMID 34356066, 2021). "The poly(adenosine diphosphate-ribose) polymerase (PARP) inhibitors show survival benefits in ovarian cancer patients with BRCA1/2 mutation or homologous recombination (HR) deficiency, but only limited efficacy in HR-proficient ones." (PMID 34552062, 2021). "BRCA1/BRCA2—both related to the homologous repair of DNA double-strand breaks—are the major breast/ovarian cancer susceptibility genes." (PMID 34287479, 2021). "The mean age of ovarian cancer diagnosis of the 54 cases with BRCA1 or BRCA2 mutations was 57.5 years, which is higher than the mean age observed in other regions of Central Europe." (PMID 33478551, 2021). "BRCA deficiency (BRCAness) underlined by germline mutations in the BRCA1/2 genes is typical for hereditary breast and ovarian cancers but also occurs in sporadic cases of these and other tumors." (PMID 33671579, 2021). "A study on hereditary breast cancer/ovarian cancer revealed that the mutations in BRCA1, BRCA2, RAD51, PALB2, and PRIP1 are associated with the ICL repair pathways." (PMID 34712221, 2021). "Nearly all patients with a BRCA1 mutation develop G3 grade ovarian cancer with poor histopathological differentiation, where differences in the expression of the examined proteins should be even more pronounced." (PMID 34205023, 2021). "A recent study in ovarian cancer reported that loss of endogenous BRCA1 dampens the tumor suppressive/growth inhibitory effect of TGFβ." (PMID 33590419, 2021). "PAF-AH expression was investigated in ovarian cancer tissue, serum of BRCA1-mutated patients, and in vitro in four ovarian cancer cell lines." (PMID 34206491, 2021). "For ovarian cancer, the risk is 17% and 44% for BRCA1 and BRCA2 variant carriers, respectively, by the age of 80." (PMID 35008774, 2021). "In fact, the results of the recently published Imagyn050 study showed that ovarian cancer patients with BRCA1/2 gene mutations were insensitive to immunotherapy, suggesting that not all DDR or HRR genes can be considered prognostic factors for immunotherapy." (PMID 35087742, 2021). "Women carrying BRCA1 pathogenic variant have a significant life time risk of breast and ovarian cancers as high as 84%." (PMID 33477375, 2021). "Nevertheless, in a BRCA1-deficient mouse model of ovarian cancer, the percentage of the intratumour Treg cell population was not modified after olaparib treatment." (PMID 34885119, 2021). "The BARD1-CA125 tests proved to be specifically sensitive for the detection of ovarian cancer in women with BRCA1/2 or BARD1 mutations." (PMID 34201956, 2021). "The well-established potent PARP inhibitor, Olaparib, exhibited a significantly high genotoxic activity in all cases, and in particular against the BRCA1 mutated UWB1.289 ovarian cancer cells." (PMID 34440232, 2021). "Transcriptomic landscapes of breast and ovarian cancers show considerable variation depending on the affected gene (BRCA1 or BRCA2) as well as the mutation type (somatic or germline)." (PMID 33525353, 2021). "According to previous reports, the highest proportion of BRCA1/2 mutation in Chinese ovarian cancer patients was 28.5%." (PMID 35071013, 2021).